KRT5 (keratin 5)
Diseases named in the same sentence as KRT5 in open-access papers (continued):
Sharing a sentence is not in itself a finding about the gene and the disease.
mesothelioma (43 papers, 2008 to 2026). A usually malignant and aggressive neoplasm of the mesothelium which is often associated with exposure to asbestos. "The most sensitive IHC markers for mesothelioma include calretinin, cytokeratin 5/6, and Wilms’ tumor (WT-1)." (PMID 36171577, 2022). "Immunohistochemical staining with calretinin and cytokeratin 5/6 is also used for diagnosis, as these stains are specific to mesothelial cells and act as positive markers in the diagnosis of mesothelioma." (PMID 33964719, 2021). "PM cells, referred as PM27 in the present work, express mesothelin, vimentin and keratin 5, considered as typical markers of mesothelioma." (PMID 30651596, 2019). "As regards the remaining mesothelioma-related markers, Keratin 5/6 and Mesothelioma-Ab1 antibodies were positive in 5 (5.7%) and 3 (3.4%) cases, respectively." (PMID 24987706, 2014). "The expression of mesothelioma-related markers (D2-40, Calretinin, Keratin 5/6, WT1, and Methotheioma-Ab1) was investigated in 87 cases of meningiomas and compared to EMA expression." (PMID 24987706, 2014). "The expression of general mesothelioma markers (mesothelin, cytokeratin 5/6, calretinin, HBME-1, thrombomodulin, and WT-1) in spheroids is consistent with those of mesothelioma specimens." (PMID 22737246, 2012). "Again, immunohistochemistry can help in the differentiation of mesothelioma and markers such as mesothelin, cytokeratin 5/6, calretinin, thrombomodulin and WT-1 have been used." (PMID 19099560, 2008). "The most specific and sensitive markers for mesothelioma are mesothelin (in epithelioid mesothelioma), calretinin and cytokeratin 5/6." (PMID 19099560, 2008). "As expected, mesothelioma cancer markers KRT5 and WT1 were upregulated in mesothelioma compared to mesothelium." (PMID 32664372, 2020). "In this study, the expression of well-established mesothelioma markers (Calretinin, Keratin 5/6, and WT1) in addition to new markers (D2-40 and Mesothelioma Ab1) was investigated in 87 meningioma cases and compared to EMA expression." (PMID 24987706, 2014). "Although pankeratin and D2-40 can be positive in both malignancies, as also demonstrated in a number of our cases, calretinin, keratin 5/6, keratin 7, and WT1 are typically distinguishing mesotheliomas." (PMID 24986479, 2014). "Interestingly, when we used antibodies against cytokeratin 5 (CK5) and calretinin to confirm the areas of mesothelioma, we observed higher expression of DR4 and DR5, where CK5 or calretinin is expressed." (PMID 34597666, 2021). "The negative to rare expression of well-established mesothelioma-related markers (Calretinin, Keratin 5/6, and WT1) demonstrated in meningioma cases in our study contrasts with their known patterns of expression in mesothelioma." (PMID 24987706, 2014). "One review noted that only 13% of human sarcomatous mesotheliomas were positive for cytokeratin 5/6 and none were positive for seven other epithelial markers." (PMID 24405760, 2014).
breast tumors (41 papers, 2007 to 2025). "Overexpression of ANGPTL4 was associated with inferior outcome for young women with basal breast tumors; the same held true for the keratins (KRT5, KRT6A, and KRT6B) among young women with HER2-enriched breast cancer." (PMID 25999348, 2015). "Compared to Caucasians, African Americans showed a higher, whereas Japanese showed a lower prevalence of basal-like breast tumour subtype (triple negative and cytokeratin 5/6+ and/or HER1+), with associated poorer prognosis for African American women and better prognosis for Japanese women." (PMID 20932344, 2010). "They indicated that most responsive breast tumors had the highest expression of Keratin 5/7 (KRT5/KRT17) and the lowest expression of endogen receptor (ER), progesterone receptor (PR) or human epidermal growth factor receptor-2 (HER2)." (PMID 28446239, 2017). "In their hierarchical clustering analyses, basal-like breast tumors were grouped together within a tight cluster showing high expression of basal cytokeratin genes (KRT5 and KRT17) and low expression of luminal estrogen receptor gene (ESR1)." (PMID 23049873, 2012). "Forty-eight (94%) triple-negative breast tumors and 18 (17%) luminal breast tumors were clustered together, showing prominent basal-like characteristics where basal marker genes KRT5 and KRT17 were markedly up-regulated." (PMID 23049873, 2012). "Numerous studies have shown that immunohistochemistry for hormone and EGFR receptors and cytokeratin 5/6 expression is a simple and workable way to determine the intrinsic subtype of breast tumors for clinical applications." (PMID 20520798, 2010). "Three of the four genes were overexpressed in breast tumors arising in younger women compared to older women: BUB1 (Fold Change 1.67, p = 0.029), KRT5 (Fold Change 1.56, p = 0.002), and MYCN (Fold Change = 1.16, p = 0.027)." (PMID 25999348, 2015). "Eighty-six breast tumors and one normal breast sample from the UNC337 database, including 20 claudin-low tumors, were evaluated using dual immunofluorescence (IF) staining with epithelial (keratin 5/19) and mesenchymal (vimentin) markers." (PMID 20813035, 2010).
triple-negative breast carcinoma (38 papers, 2009 to 2025). An invasive breast carcinoma which is negative for expression of estrogen receptor (ER), progesterone receptor (PR), and human epidermal growth factor receptor 2 (HER2). "Triple negative breast cancers (TNBCs) are known to express low PGR, ESR1, and ERBB2, and high KRT5, KRT14, and KRT17." (PMID 30335837, 2018). "On the other hand, the C19MChigh group harbored significantly upregulated expression of KRT5, KRT14 and KRT17 mRNAs compared to C19MClow group, the candidate “positive markers” of basal-like triple negative breast cancers (TNBCs)." (PMID 30335837, 2018). "Several basal-related genes directly corresponding to expression levels of cytokeratins and EGFR protein marker, including KRT5, KRT6C, KRT6E, KRT14, and EGFR genes, were found to be extensively up-regulated in triple-negative breast cancer." (PMID 23049873, 2012). "Similarly, the BC_P05T subcluster is characterised by elevated KRT5 expression and is primarily regulated by the transcription factor HOXB2, which restricts the occurrence of triple-negative breast cancer by reshaping the extracellular matrix." (PMID 39877290, 2025). "Keratin 5 (KRT5), a member of the microfibrillar keratin type II family, which serves as a biomarker for several types of cancer, including lung cancer and triple-negative breast cancer was found to be specific to the NE-low tumor subset." (PMID 34200100, 2021). "Absence or low HER3 expression correlated with clinically aggressive features, such as triple-negative breast cancer (TNBC) phenotype, basal cell origin (cytokeratin 5/14 expression combined with ER negativity), large tumour size, and positive lymph node status." (PMID 30367623, 2018). "The normal breast-like subtype is also known as triple-negative breast cancer (TNBC), because it lacks expression of HER2, ER, and PgR; however, unlike the basal-like subtype, which similarly lacks these three hormone receptors, TNBC is also negative for keratin 5 (CK5) and EGFR expression." (PMID 37432459, 2023).
lung carcinoma (36 papers, 2009 to 2025). "According to previous work, it was revealed that abnormalities in KRT5 is leading cause of many cancers like lung cancer, ovarian cancer and prostate cancer." (PMID 40653567, 2025). "A subsequent effort tested Ad-K5-Cre, previously used in lung cancer studies, which employs a different basal keratin gene promoter, Krt5 (K5)." (PMID 40622584, 2025). "No SGM-101 fluorescence, no CEACAM5 staining, and no other immunohistochemical staining were associated with markers of lung malignant neoplasms, including thyroid transcription factor 1 (TTF-1), cytokeratin 5/6 (CK 5/6), and p63 (eFigure 6 in Supplement 2)." (PMID 36705924, 2023). "Cell cluster-specific genes coalesced the 25 clusters into four major groups: CNV−MOG+ normal glial cells, KRT5+ lung cancer (LC) metastasis cells, CD45 (PTPRC)+ immune cells and CNV+ malignant tumor cells." (PMID 34692159, 2020). "These genes are known to be highly expressed in SCC and KRT5 and p63 IHC are important markers in diagnostics of lung cancer." (PMID 32620126, 2020). "Adenosquamous carcinoma (ASC) is an aggressive type of lung cancer that contains a mixture of cells with squamous (cytokeratin 5+) and adenocarcinoma (cytokeratin 7+) phenotypes." (PMID 24324581, 2013). "Interestingly, within the tumor clusters, 12 expressed glioma cell marker genes, and one other cluster specifically expressed the lung cancer marker KRT5, indicative of lung cancer metastasis." (PMID 38994023, 2024). "Prognostic associations of KRT5 and KRT14 have been implicated in lung cancer, while the relationship and molecular mechanisms of KRT6A and KRT17 in the lung cancer are still unknown and should be further elucidated." (PMID 27684953, 2016). "For example, KRT5, KRT6A, KRT14, and DSG3 in LUSC25, and NKX2.126, SFTA227 in LUAD have been evidently proved directly correlated to the lung cancer diagnosis and progression." (PMID 40654610, 2025). "For example, KRT5,KRT6A, KRT14, and DSG3 (All of these genes shown are with an adjustedp-value < 1e–200) in LUSC, and NKX2.1, SFTA2 (All of these genes shown are with anadjusted P-value < 1e–200) in LUAD have beenevidently proved directly correlated to the lung cancer diagnosis andprogression." (PMID 41347120, 2025).
prostate carcinoma (35 papers, 2004 to 2026). A carcinoma that arises from epithelial cells of the prostate gland. "In PCa, expression of KRT8, KRT18, and KRT19 by tumor cells disseminated to the bone, is associated with a worse prognosis; KRT18 and KRT5 expression correlates with metastases and hormone-escaped prostate carcinomas, respectively." (PMID 36033462, 2022). "Of the 23 HRD-related genes, most were protective factors for PFS of patients with prostate cancers, except KRT5 and DDC." (PMID 35836192, 2022). "In prostate cancer initiation, emergence of a discontinuous KRT5 (most prominent CK5) basal layer is a hallmark of the transformation process and defines precancerous prostate intraepithelial neoplasia (PIN) lesions." (PMID 27711225, 2016). "The pattern of S100A6 expression in benign epithelium and adenocarcinomas is similar to that of cytokeratin 5 and that reported for p63 and 34βE12, and therefore has the potential to be used as an adjuvant to these markers in the diagnosis of prostate cancer." (PMID 15280928, 2004). "Furthermore, prostate cancer organoids and their corresponding tissues were analyzed by immunohistochemical profiling of Cytokeratin 5/6 (CK5/6), Cytokeratin 8 (CK8), and Androgen Receptor (AR)." (PMID 41463218, 2025). "Additionally, it was reported that the expression of miR-601 exhibited low level in prostate cancer stem cells, and miR-601 also inhibited the proliferation of pancreatic cancer cells by targeting and regulating KRT5." (PMID 33955831, 2021). "The most interesting ones appeared to be claudin 3 (CLDN3) and alpha-methysacyl-CoA racemase highly expressed in prostate cancer and filamin C (FLNC) and keratin 5 with highest expression in normal prostate tissue." (PMID 24477410, 2014). "Accordingly, prostate cancer (PC) foci are generally characterized by expression of luminal keratins (KRT 8/18) and absence of KRT5/14." (PMID 27711225, 2016).
lung adenocarcinoma (30 papers, 2013 to 2026). A carcinoma that arises from the lung and is characterized by the presence of malignant glandular epithelial cells. "TTF1, KRT7, SOX2, P63, and KRT5 are biomarkers for poor prognosis of lung adenocarcinoma and lung squamous cell carcinoma." (PMID 38248716, 2023). "High expression was also found to prevent lung adenocarcinoma by inhibiting keratin 5 (KRT5) expression." (PMID 34769348, 2021). "(C) Merged high-power image of SFTPC and KRT5 co-staining of human lung adenocarcinoma (n = 10) shows significant co-localization of the two markers in a subset of tumor cells (arrows)." (PMID 31140976, 2019). "Lung adenocarcinoma (LUAD) and lung squamous carcinoma (LUSC) were well classified by the high expression of NAPSA and TTF-1 (NKX2-1) for LUAD and TP63 and CK5 (KRT5) for LUSC." (PMID 35541919, 2022). "Pre-invasive lesions and tumours expressed the LUSC markers KRT5 and P63 and lacked expression of the lung adenocarcinoma (LUAD) marker surfactant protein C (SPC)." (PMID 34385275, 2022).
melanoma (24 papers, 2014 to 2026). A malignant, usually aggressive tumor composed of atypical, neoplastic melanocytes. "The expression level of the KRT5 gene was significantly lower in metastatic melanoma than in primary melanoma, and it was confirmed in vitro experiments that KRT5 knockdown promoted cell proliferation, migration, and invasion of MM67." (PMID 39003418, 2024). "We also found genes that are associated with melanoma metastases formation (CCL8, CD38) and melanoma cell migration and invasion (KRT5)." (PMID 38671536, 2024). "We suppressed the KRT expression in melanoma A375 cells through KRT5-specfic siRNAs and then performed the in vitro experiments to clarify the effects of KRT5 on cell proliferation, migration, and invasion of melanoma." (PMID 35054979, 2022). "The possible effect of KRT5 on melanoma metastasis were preliminarily investigated through in vitro biological experiments." (PMID 35054979, 2022). "The experimental results showed that KRT5 knockdown can significantly enhance the cell metastasis capacities in melanoma, including cell proliferation, migration, and invasion." (PMID 35054979, 2022). "Kaplan–Meier survival analyses showed that FLG, KRT5, DSG1, DSG3, and IVL expression levels were significantly associated with melanoma patient survival (p < 0.01)." (PMID 33178610, 2020). "A knockdown of KRT5 significantly increased melanoma cell migration and invasion." (PMID 38671536, 2024). "In general, the hub genes, including KRT5, IVL, and DSP, and key pathways associated with melanoma metastasis defined in the present study may provide new insights into clinical melanoma treatment." (PMID 35054979, 2022). "The in vitro experiments showed that KRT5 played the inhibitory effects on melanoma metastasis." (PMID 35054979, 2022). "Additionally, the effects of KRT5 on cell proliferation and cell metastatic behaviors of melanoma were determined by in vitro experiments." (PMID 35054979, 2022). "In addition, researchers believed that KRT5 participated in melanoma cell structure, metastasis and recurrence, which is consistent with our findings." (PMID 33441834, 2021). "Elevated expression of KRT5 was detected in recurrent and metastasized melanoma cell." (PMID 33441834, 2021). "Notably, KRT5 was confirmed to play inhibitory effect on melanoma metastasis." (PMID 35054979, 2022). "Finally, KRT5-specific siRNAs were utilized to reduce the KRT5 expression in melanoma A375 cells." (PMID 35054979, 2022). "High expression of KRT5 could predict poor prognosis in melanoma patients." (PMID 33441834, 2021). "When implanted in thymectomized mHM, which were subsequently engrafted with patient melanoma tissue (autologous, or mHMTA), sTOs expressed thymic tissue markers EPCAM, KRT5, and KRT8 and contained developing double-positive T cells." (PMID 41129601, 2025). "In the present study, the downregulation of the KRT5, IVL, and DSP expressions implied inhibitory effects of these genes in melanoma metastasis." (PMID 35054979, 2022). "Therefore, KRT5 may serve important roles in melanoma metastasis." (PMID 35054979, 2022). "KRT5 has been shown to inhibit melanoma metastasis 21, while studies have suggested that a lack of KRT5 and KRT7 can impede ovarian cancer cell migration." (PMID 38495507, 2024). "This study suggests that the circulating proteins ASIP, KRT5, CTSS, and TNFSF8 are causally associated with melanoma and non-melanoma skin cancer-related traits through a multicenter Mendelian randomization." (PMID 39003418, 2024). "Overall, KRT5, IVL, and DSP might represent potential functions for the prevention and treatment of melanoma metastasis." (PMID 35054979, 2022). "In this study, we highlighted that KRT5, IVL, and DSP may serve as novel targets to suppress melanoma metastasis." (PMID 35054979, 2022). "It is noticeable that the functional characteristics of KRT5, IVL, and DSP in melanoma have not been fully explored, especially in melanoma metastasis." (PMID 35054979, 2022).
psoriasis (24 papers, 2011 to 2025). An autoimmune condition characterized by red, well-delineated plaques with silvery scales that are usually on the extensor surfaces and scalp. "Keratin-5 expression in suprabasal layers, a hallmark of keratinocyte hyperproliferation in psoriasis, was remarkable in mice injected with IL-23 and TL1A." (PMID 38348035, 2024). "In the dynamic evolution process of EMT in psoriasis, as the KC marker Krt5 increased, the EMT markers Vim and Zeb2, and the IL-17 signalling pathway marker Il17ra clearly decrease." (PMID 38472183, 2024). "In comparison with normal samples, the glycolysis score was significantly higher in psoriasis samples in KRT5+ KRT14+ KC, KRT1+KRT10+ KC, and LDHA+SLC2A1+ KC (all P<0.001)." (PMID 37205116, 2023). "KRT15, KRT24, KRT31, KRT37, KRT78 are differentially expressed in psoriasis, while KRT5 and KRT14 are specific for AD." (PMID 35874668, 2022). "To assess whether FZHFZY influences epidermal differentiation in the skin of mice with IMQ-induced psoriasis, we detected the expression of loricrin, filaggrin, involucrin, keratin 5, keratin 14 and keratin 15 in the skin by RT-PCR and western blotting." (PMID 34456715, 2021). "qPCR results revealed significantly increased expression of Lcn2, Tnfsf12, Il1b, Krt5, and Krt10 mRNA in the skin of Fn14–/– mice with IMQ-induced psoriasis." (PMID 40369189, 2025). "Other psoriasis-specific enriched pathways included lipid metabolism (e.g. ACOT4, S1PR3), keratinization (e.g. LCE5A, KRT5/7/16), neutrophil degranulation, and antimicrobial peptides (e.g. LTF, DEFB4A, S100A7-9)." (PMID 38433843, 2024). "In our study, there is downregulated expression of loricrin, filaggrin and involucrin, but elevated expression of keratin 5, keratin 14 and keratin 15 in IL-17A/IL-22/IFN-γ/TNF-α–induced HaCaT cells and in mice with IMQ-induced psoriasis." (PMID 34456715, 2021). "Furthermore, as the KC marker Krt5 increased, the EMT markers Vim and Zeb2, and the IL-17 signalling pathway marker Il17ra clearly decreased, which hinted at the existence of EMT in psoriasis and its intimate connection with the IL-17 signalling pathway." (PMID 38472183, 2024). "As negative control for Lrig1 staining, we stained psoriatic epidermis and confirmed the total lack of Lrig1 signal, while expression of keratin 5 was normally detected in keratinocytes of the basal layer in SAHE, HHE and psoriasis." (PMID 28099467, 2017). "Proteins specific to the basement membrane region (KRT14, KRT5, KRT1) were decreased only slightly in psoriasis lesions with no significant overall trend (p = 0.346)." (PMID 26251673, 2015).